GATA1 (GATA binding protein 1)
Diseases named in the same sentence as GATA1 in open-access papers (continued):
Sharing a sentence is not in itself a finding about the gene and the disease.
dyserythropoietic anemia (14 papers, 2008 to 2022). "Diamond‐Blackfan anaemia (DBA) shares clinical features with two recently reported sporadic cases of dyserythropoietic anaemia with a cryptic GATA1 splicing mutation (c.871‐24 C>T)." (PMID 35846220, 2022). "Germline GATA1 pathogenic variants in the N-terminal zinc finger (N-ZF) are typically associated with X-linked thrombocytopenia, platelet dysfunction, and dyserythropoietic anemia." (PMID 36291092, 2022). "Disruption of the zinc finger motifs in GATA-1, such as produced by germline mutations, compromises the function of this critical transcription factor and causes dyserythropoietic anemia." (PMID 33149232, 2020). "This is not only illustrated by the observation that pro-erythroblasts from chimeric GATA-1 knockout mice fail to mature beyond this stage and go into apoptosis but also by individuals carrying mutations in the GATA1 gene who suffer from dyserythropoietic anemia." (PMID 28210260, 2017). "Mutations in GATA1 can lead to dyserythropoietic anemia and pseudo gray-platelet syndrome." (PMID 27152938, 2016). "Recently, two patients were reported with dyserythropoietic anemia and an intronic substitution in GATA1 gene that is 24 nucleotides upstream of the canonical splice acceptor site." (PMID 32555368, 2020). "For example, the concept GATA1 Gene is missing the role disease with the target Dyseryth-ropoietic Anemia." (PMID 19221606, 2008). "Other very rare types of CDA are caused by autosomal dominant mutations in KIF23 (Kinesin Family Member 23, CDA type III), KLF1 (Kruppel-Like Factor 1, CDA type IV) or X-linked mutations in GATA1 (GATA Binding Protein 1, X-linked thrombocytopenia with or without dyserythropoietic anemia)." (PMID 33672223, 2021).
myeloid leukemia (14 papers, 2015 to 2025). A clonal proliferation of myeloid cells and their precursors in the bone marrow, peripheral blood, and spleen. "Myeloid leukemia associated with DS (ML-DS) is preceded by a preleukemic phase called transient abnormal myelopoiesis driven by GATA1 gene mutations and progresses to ML-DS via additional mutations in cohesin genes, CTCF, RAS, or JAK/STAT pathway genes." (PMID 37895004, 2023). "With this in mind, we investigated the levels of SDHC variants and the oxidative mitochondrial metabolism in myeloid leukemia K562 cells over-expressing GATA-1 isoforms." (PMID 34679737, 2021). "This has been associated with GATA1 mutations, which primarily drive myeloid leukemia of DS." (PMID 40913257, 2025). "Furthermore, data from TAM and myeloid leukaemia patients provided substantial support to our study by showing that miR-1202 down-modulation is accompanied by increased GATA-1 levels, with more marked effects on GATA-1S." (PMID 38350611, 2024). "The ML-DS patients also possess the pathognomonic mutation in GATA1; such mutations are absent in other subtypes of myeloid leukemia." (PMID 33102613, 2020). "Myeloid leukemia in DS (ML‐DS) cases were not included in our study, but we were able to investigate whether epigenetic age may be associated with somatic GATA1 mutations at birth, which can progress to ML‐DS in up to 10% of patients." (PMID 35661546, 2022). "For example, two isoforms of GATA1, GATA1-FL and GATA-1S, exert distinct effects on redox homeostasis in K562 human myeloid leukemia cells." (PMID 39456519, 2024). "Molecular investigations of myeloid leukemia cell lines revealed the presence of binding sites for ubiquitous (NF-1 and SP-1) and myeloid enriched (MZF-1-like protein, GATA-1, and Ets-1) transcription factors in the promoter region of the gene." (PMID 31709175, 2019).
colorectal cancer (13 papers, 2012 to 2025). A primary or metastatic malignant neoplasm that affects the colon or rectum. "Recent studies have shown the association of RUNX1 and RUNX2 with TGF-beta signalling pathways in colorectal cancer, suggesting a potential association of GATA-1 with CRC through RUNX1SP1." (PMID 22852817, 2012). "The tumor-promoting role of GATA1 has been witnessed in human malignancies such as ovarian cancer and colorectal cancer by promoting cell proliferation and invasiveness." (PMID 35491849, 2022). "Thus, the miRNA signature may affect the survival prognosis of colorectal cancer patients and the colorectal cancer progression through regulating GATA1." (PMID 31799184, 2019). "GATA-binding protein 1 (GATA1) participates in tumor progression by activating JAG1/Notch and PI3K/AKT pathways in ovarian and colorectal cancer, respectively." (PMID 38254939, 2023). "GATA-1 promotes cell proliferation, migration, and invasion via activating the PI3K/AKT signaling pathway in colorectal cancer." (PMID 31783675, 2019).
acute myeloid leukemia (10 papers, 2012 to 2024). Acute myeloid leukemia (AML) is a group of neoplasms arising from precursor cells committed to the myeloid cell-line differentiation. "This includes common categories like UBTF, GLISr and GATA1, which were otherwise categorized as “acute myeloid leukemia, myelodysplasia-related” or “acute myeloid leukemia, other defined gene alteration” in the current WHO classification." (PMID 37398194, 2023). "Approximately 20% of children with TAM progress to Acute Myeloid Leukemia (AML) when persistent GATA1 mutant cells acquire additional mutations, most frequently in genes encoding members of the cohesin protein family, epigenetic regulators and signaling molecules." (PMID 35805057, 2022). "These include common categories like UBTF, GLISr and GATA1, otherwise categorized as ‘AML-MR’ or ‘acute myeloid leukemia with other defined gene alterations’ in the current WHO classification." (PMID 38212634, 2024). "It has been previously shown that acute myeloid leukemia (AML) patients with higher levels of GATA1 expression have poorer outcomes." (PMID 23874683, 2013). "Disturbance of mRNA expression of erythroid transcription factors, such as EKLF, GATA1 or GATA2, has been shown in patients with acute myeloid leukemia (AML), but no direct link to the mutations responsible for leukemogenesis has been demonstrated." (PMID 22676581, 2012).
erythroleukemia (10 papers, 2012 to 2024). Acute erythroid leukemia characterised by the presence of at least 50% erythroid precursors and at least 20% myeloblasts in the bone marrow. "In contrast, some mice with 95% reduced Gata1 mRNA expression due to a knockdown mutation (Gata1+/1.05) developed a late-onset B-cell lymphoproliferative disease or an earlier erythroleukemia-like disease." (PMID 32533074, 2020). "Moreover, some adult female mice that are heterozygous for the targeted disruption of the X chromosome-linked Gata1 promoter region displayed reduced Gata1 gene expression (Gata11.05/X allele) and developed an early onset erythroleukemia-like disease." (PMID 32533074, 2020). "The FLI1 gene, encoding for another ETS transcription factor, was also first studied in erythroleukemia virus models, and its overexpression reduces GATA1 expression and impairs erythroid differentiation." (PMID 38892446, 2024). "These alterations lead to aberrant activity of erythroid transcriptional master regulators like GATA1, indicating that erythroleukemia will most likely require combinatorial targeting for efficient therapeutic interventions." (PMID 33898929, 2021). "Moreover, engineering mice with an inducible expression of the fusion EWS/FLI-1 resulted in the rapid development of erythroleukemia expressing GATA1." (PMID 38892446, 2024). "Is GATA1 a core player in the pathogenesis of human erythroleukemia?" (PMID 33898929, 2021). "Moreover, previous research from our group has shown that ribosome regulation mediated by the cell-fate transcription factors PU.1 and GATA-1 is an integral part of erythroleukemia differentiation." (PMID 33572085, 2021).
X-linked thrombocytopenia (10 papers, 2016 to 2022). "Substantial studies have documented that mutations in the GATA1 gene results in X-linked thrombocytopenia with thalassemia and X-linked thrombocytopenia with dyserythropoietic anemia." (PMID 35771876, 2022). "A mutation in exon 4 of the GATA1 gene is associated with X-linked thrombocytopenia with thalassemia (OMIM 314050), which is a severe bleeding disorder." (PMID 34576024, 2021). "X-linked thrombocytopenia with thalassemia and X-linked thrombocytopenia with dyserythropoietic anemia are both caused by mutations in GATA1, resulting in impaired MK and erythroid cell maturation." (PMID 31275945, 2019). "The only GATA1 mutationreported in hereditary X-linked thrombocytopenia with thalassemia is the missense mutationR216Q which is located in the DNA binding surface of the GATA1 N-terminal zinc finger andresults in reduced DNA binding rather than affecting GATA1–FOG1 interaction (Ref." (PMID 26953528, 2016). "Further, a mutation in the N-finger of the GATA1 gene, abrogating the interaction between GATA1 and FOG1, showed associations with X-linked macro-thrombocytopenia, non-X-linked thrombocytopenia and dyserythropoiesis." (PMID 26910538, 2016). "In humans, several mutations affecting the GATA1 gene have been described, which lead to a broad spectrum of defects, including X-linked thrombocytopenia (XLT), X-linked thrombocytopenia with thalassemia (XLTT) and transient myeloproliferative disorder (TMD)." (PMID 27152938, 2016).
ovarian carcinoma (9 papers, 2021 to 2024). A malignant neoplasm originating from the surface ovarian epithelium. "GATA1 was recently reported as involved in tumorigenesis, cancer progression 43, 44, and carboplatin resistance in ovarian cancer." (PMID 38169528, 2024). "It was also suggested that in ovarian cancer, GATA1-regulated JAG1 plays a key regulatory role in cancer cell proliferation and metastasis." (PMID 39684309, 2024). "CCLE analysis demonstrated that although the mRNA expression levels of GATA1 and GATA2 ranked the 14th and 16th highest in OC among different cancer cell types, the expression levels of GATA1 and GATA2 in ovarian cancer cells are generally low, (shown in green frame)." (PMID 35488350, 2022).
myelodysplastic syndrome (8 papers, 2015 to 2026). A clonal hematopoietic disorder characterized by dysplasia and ineffective hematopoiesis in one or more of the hematopoietic cell lines. "We demonstrate that alternative splicing of GATA1 is seen in myelodysplastic syndrome and results in shorter functionally hypomorphic isoform." (PMID 40424086, 2025). "For example, SF3B1 mutations in myelodysplastic syndromes specifically impair the erythroid lineage by inducing mis-splicing of MAP3K7, which leads to p38 MAPK inactivation and premature downregulation of GATA1, thereby blocking terminal erythroid differentiation." (PMID 41360772, 2025). "GATA1 expression and transcriptional activity are dynamically regulated during erythroid differentiation, and its dysregulation can lead to a range of hematological disorders, including polycythemia vera (PV) and myelodysplastic syndromes (MDS)." (PMID 41521666, 2026). "The N-terminally truncated GATA1 mutation is unique to TMD/DS-ML and is absent in DS-ALL, DS-Myelodysplastic syndrome (DS-MDS), DS infants without hematological disorders, non-DS-AML." (PMID 34685678, 2021). "This has been described in myelodysplastic syndrome (MDS) patients, where a low expression of HEMGN contributes to intranuclear delocalization of GATA1 and may contribute to the worsening of ineffective erythropoiesis." (PMID 39519257, 2024).
COVID-19 (7 papers, 2021 to 2026). A disease caused by infection with severe acute respiratory syndrome coronavirus 2. "These publications indicate that the taste or smell loss in COVID-19 patients is related to in situ odor dysfunction, which the gene EDRF1 also participated in through the GATA-1-mediated pathway." (PMID 36983953, 2023). "Further, sustained decrease in testosterone levels along with the downregulated steroidogenesis genes (GATA6 and GATA1) indicate a long-term impact on LC function and aligns well with clinical data showing decreased testosterone levels in COVID-19 patients for up to 7 months after recovery." (PMID 39775442, 2025). "A deeper understanding of the mechanism by which GATA-1 represses CCR5 expression can help unravel the genetic regulation of CCR5 in the target cells of COVID-19 and may be valuable in devising new approaches to antagonize CCR5 in individuals with COVID-19 infection." (PMID 34753980, 2021). "HSPCs differentiation-related genes, such as GATA1 and GATA2, were significantly downregulated in the COVID-19 group." (PMID 37446049, 2023). "This was reflected by increased expression over time of genes involved in heme metabolism (such as ABCG2 and GATA1) until they were no longer significantly differentially expressed compared to non-COVID-19 sepsis patients by D7." (PMID 37090709, 2023).
thalassemia (7 papers, 2016 to 2024). An inherited blood disorder characterized by a decreased synthesis of one of the polypeptide chains that form hemoglobin. "In our study, we observed increased expression of GATA1 (the master regulator of erythropoiesis) and other genes involved in erythroid differentiation in patients with thalassemia and SCD." (PMID 39519257, 2024). "The importance of GATA1 in the context of thalassemia has also been underscored by the discovery that the globin chain imbalance, which is characteristic of this disorder, indirectly influences GATA1 activity." (PMID 35682828, 2022). "In addition, other modifiers were also shown to affect thalassemia phenotype, such as mutations in the molecular chaperone haemoglobin stabilizing protein (AHSP) and transcription regulator GATA1." (PMID 34650160, 2021). "GATA1 mutations are also detected in a specific form of X-linkedhereditary thrombocytopenia and are described with and without thalassemia." (PMID 26953528, 2016).
breast tumor (6 papers, 2015 to 2020). "Examples are 269 TF knockout microarrays used for genome-scale investigation of eukaryotic gene regulation, Gata1 knockout to identify GATA1-responsive genes, and tumor cell-specific Twist1 knockout to study the effect of Twist1 on breast tumors in vivo." (PMID 31598675, 2020). "GATA-1 associates with the histone methyltransferase SET7 to promote VEGF transcription and breast tumor angiogenesis." (PMID 31783675, 2019). "Here, we show that transcription factor GATA1 associates with the histone methyltransferase SET7 to promote VEGF transcription and breast tumor angiogenesis." (PMID 26848522, 2016). "SET7 was required for GATA1-induced breast tumor angiogenesis and growth in nude mice." (PMID 26848522, 2016). "To explore the clinical significance of GATA1 and SET7, we conducted immunohistochemistry (IHC) of 80 human breast tumor samples." (PMID 26848522, 2016). "These signature genes are densely connected, among which several, such as ESR1, FOXA1, NQO1, GATA1, ALDH3B2, keratins, are well-known players driving the heterogeneity and carcinogenesis of breast tumors." (PMID 26404658, 2015).
depression (6 papers, 2014 to 2024). "We selected 4 proteins to check for their respective mRNA levels.(i)Gata1 is a transcription factor that has been shown to be associated with depression." (PMID 38802853, 2024). "GATA1 is known to repress transcription of synaptic genes like Syn1, Camk2a, and Rab3a, and associated with Major Depressive Disorder in human patients." (PMID 29743870, 2018). "In addition, up-regulation of GATA1 has been reported to negatively regulate synaptic genes, and GATA1 up-regulation has been associated with major depression disorder." (PMID 34890016, 2022). "Indeed, in the socially isolated Wdr13-/0 mice, there was an up-regulation of GATA1 – a transcription factor that negatively regulates synaptic genes and has been associated with Major Depression (MD) in humans." (PMID 29743870, 2018). "Using the results of the multi-omics data analysis, we focused on immune activation by the increased level of GATA1 in the CNS, which was observed in the dlPFC of patients with depression." (PMID 38784708, 2024). "In a previous study, we demonstrated the increased expression of GATA1 in the dorsolateral prefrontal cortex (dlPFC) of patients suffering from depression and described its role as a transcriptional repressor of synapse-related genes." (PMID 38784708, 2024). "Increased levels of GATA1 have been reported in post-mortem samples of clinically depressed individuals and the overexpression of GATA1 led to a phenotype of depression-like-symptoms in rat, which was similar as in the socially isolated Wdr13-/0 mice." (PMID 29743870, 2018). "However, in Major Depression and in rodent model of depression, it is known that GATA1 gets upregulated." (PMID 29743870, 2018). "Our results predicted a possible role of WDR13 in regulation of GATA1 and it appeared likely that the absence of Wdr13 predisposed mutant mice to Major Depression-like phenotype when subjected to social isolation stress through this master regulator." (PMID 29743870, 2018). "Hence, Gata1 expression might be directly correlated with depression like phenotype of socially isolated Wdr13-/0 mice." (PMID 29743870, 2018). "Further evidence for a role of GATA1 in depression was provided by a recent genome microarray study of postmortem MDD subjects, which showed that levels of GATA1 mRNA were increased in the DG, but not CA1 subregion of the hippocampus." (PMID 25340772, 2014).